ENSG00000202343
Synonyms: LOC124901526
Gene: Small nucleolar RNA gene on chromosome 6 (149,594,625 to 149,594,759, forward strand). Ensembl gene ENSG00000202343.
Gene Ontology:
Biological process: RNA processing
Cellular component: nucleolus
Homologues: Paralogues in human: SNORA2A (82% identical), SNORA2B (68% identical), SNORA2C (68% identical).